MMP9 (matrix metallopeptidase 9)
Diseases named in the same sentence as MMP9 in open-access papers (continued):
Sharing a sentence is not in itself a finding about the gene and the disease.
influenza (continued). "Thus, our data not only demonstrate a role for MMP9 in influenza pathogenesis, but also provide further in vivo evidence for MMP9 activity as a mechanism by which neutrophils digest the extracellular matrix to traverse the basement membrane in order to gain access to the infected lung epithelium." (PMID 22496659, 2012). "Zymography showed that smoke before influenza infection led to higher total activity of MMP-2, MMP-9 and caseinolytic proteases in BALF at d3." (PMID 18627612, 2008). "Smoke and influenza mice had increases in gene expression of MMP-7 at d3 only and of MMP-9 at d10 only." (PMID 18627612, 2008). "For both bioactive MMP-2 and MMP-9, we observed 1.9- and 1.3-fold increases early after infection (4 DPI), suggesting that both the placenta and the surrounding fetal membrane were subjected to enhanced MMP-mediated degradation as a result of influenza infection." (PMID 32922392, 2020). "Incubation of influenza-infected BALF with neutrophils did not significantly alter the gene expression of cathelicidin, S100A8, S100A9, lactotransferrin, pentraxin-3, and MMP9 (data not shown)." (PMID 23467809, 2013).
invasive breast carcinoma (19 papers, 2006 to 2025). A carcinoma that infiltrates the breast parenchyma. "IL-22R1, S1PR1, and MMP-9 were found to be predominantly expressed in metastatic breast carcinoma specimens but only weakly detected in normal tissues and invasive breast carcinoma (left)." (PMID 31935914, 2020). "The over-expression of full-length Anxa2 increased the expression of three EMT-TFs such as SLUG, SIP1 and TWIST1 and two MMPs (MMP2, MMP9) in invasive breast cancer MDA-MB-231 cells." (PMID 32244350, 2020). "Given that ANXA1 positively regulates the expression and function of MMP9 in invasive breast cancer, we believe that the sensitivity of MMP9 may be related to the effect of DCST1-AS1 on ANXA1." (PMID 32226772, 2020). "Therefore, we assessed the expression of MMP9 in invasive breast cancer cells depleted of PRMT7." (PMID 25605249, 2015). "The levels of MMP9 and MMP2 were also increased in the stroma adjacent to invasive breast carcinomas (Finak Breast)." (PMID 28423685, 2017). "Another group also regarded mPRα as a key marker of impaired prognosis for invasive breast cancer, and mPRα enhanced MMP-9 expression in the process of spreading to regional lymph nodes via the PI3K/Akt pathway." (PMID 35123491, 2022). "Surprisingly, we did not detect quantifiable levels of the pro and active MMP-9 which has been suggested to be highly expressed by invasive breast carcinomas." (PMID 16831226, 2006). "As MMP9 is thought to play a key role in tumor invasion and metastasis, we proceeded to test whether any of the seven EDS inhibitory antibodies would slow down metastasis of an invasive breast cancer line HT-1080 overexpressing MMP9." (PMID 38683990, 2024). "However, the MMP9 correlated genes were not enriched in pathway related to NETs formation when analyzing the BRCA (Breast invasive carcinoma) or CESC (Cervical squamous cell carcinoma and endocervical adenocarcinoma) dataset." (PMID 38577608, 2024). "Besides, CDK8 drives the expression of matrix metalloproteinase Mmp9, which contributes to the invasive character of several cancer cell types and regulates Ccl2 in TNBC cells, which has been found overexpressed in invasive breast cancers and is suggested to support metastasis." (PMID 34689158, 2021).
liver disease (19 papers, 2012 to 2025). "RHCC also featured Succinivibrio (3.90%) and Treponema 2 overrepresentation, which are genera implicated in gut barrier dysfunction through succinate-driven HIF-1α activation and are associated with the progression of liver diseases and hepatic fibrogenesis through MMP-9 overexpression." (PMID 41239524, 2025). "Considering the remarkable influences of MMP‐9 on angiogenesis and fibrogenesis, we hypothesized that MMP‐9 inhibition or deletion may attenuate portal hypertension and the associated derangements." (PMID 34647412, 2021). "We next looked at the levels of ALP between the various disease groups as a way to gauge for potential liver disease as another possible source for the elevated levels of total and active MMP-9." (PMID 41009467, 2025). "Significant differences in MMP-9 expression were also observed in studies conducted on patients with other liver diseases." (PMID 35625637, 2022). "In conclusion, non‐specific MMP inhibition with minocycline and relatively specific MMP‐2/MMP‐9 inhibition with SB‐3CT ameliorated liver cirrhosis and portal hypertension‐related derangements." (PMID 34647412, 2021). "In this study, all three series of experiments consistently demonstrated that MMP‐9 suppression alleviated portal hypertension." (PMID 34647412, 2021). "TNFα also modulates several matrix metalloproteinases that are involved in liver injury, repair, and remodeling, with MMP1 and MMP9 the most relevant MMPs with regards to liver disease." (PMID 26506376, 2015). "MMP-9, also known as ‘Gelatinase-B’, is secreted by a variety of immune and fibroblast cell types, and can act differently depending on the stage and etiology of hepatic diseases." (PMID 39944325, 2025). "Our results show that, after hepatic I/R injury, hepatorenal syndrome rapidly develops in rats, characterized by an increase in MMP-9-dimer and inflammatory changes such as an increase in renal cortex TNF-alpha, thus suggesting a key role for this pro-inflammatory cytokine in MMP activation." (PMID 35631351, 2022). "MMP‐9 inhibition is a possible target for the treatment of portal hypertension." (PMID 34647412, 2021). "MMP-9 is known as an indicator playing important roles in hepatic disorders." (PMID 22792126, 2012). "Therefore, the inhibition of MMP‐9 may ameliorate splenomegaly and reduce splenic blood flow while alleviating portal hypertension." (PMID 34647412, 2021). "Furthermore, MMP‐9 gene deletion effectively ameliorated portal hypertension in BDL mice." (PMID 34647412, 2021). "MMP-2, MMP-9, and FGF-19 levels were dysregulated among the HIV/HBV–co-infected, and 11% of HIV/HBV–co-infected had evidence of undiagnosed advanced liver disease." (PMID 39471521, 2025). "Of note, BDL reduced MAP and elevated PP in both WT and MMP‐9 KO mice, indicating that BDL induced the systemic and portal hemodynamic features of portal hypertension in the mice." (PMID 34647412, 2021). "MMP-9, a consequent molecules in TNF-α signaling, is known as an indicator playing important roles in hepatic disorders." (PMID 23555760, 2013). "MMP9 is a member of the MMP protein family and plays a crucial role in various hepatic disorders, including inflammatory processes, fibrogenesis, and cancers." (PMID 22792126, 2012). "Also, five proteins (HSP90B1, Protein S100-A9 [S100A9], MMP1, matrix metalloproteinase-9 [MMP9], and CSF3) in the IL17 signaling pathway are in phase III clinical trials for treating solid tumors and have the potential to treat liver diseases." (PMID 37209815, 2023). "These two cytokines, MPO and MMP-9, may act in concert with the LCN2 protein and are involved in liver diseases, such as NAFLD/NASH." (PMID 36012166, 2022). "Minocycline, a nonselective MMP inhibitor, and 3B‐SCT, an MMP‐2 and MMP‐9 inhibitor, significantly attenuated portal hypertension in rats with BDL‐induced liver cirrhosis." (PMID 34647412, 2021).
liver disease (continued). "MMP-8, MMP-9, YKL-40, and TIMP-1 serum levels were unaffected by the presence or absence of CF liver disease or pancreatic insufficiency." (PMID 25545245, 2014). "Thus, MMP-2, MMP-9 and TNF-α could not be correlated with the progression of liver disease." (PMID 26464613, 2015).
skin cancer (19 papers, 2006 to 2026). "In skin cancer, MMP-9, which is secreted from inflammatory cells, degrades the basement membrane and leads to tumor invasion." (PMID 34744703, 2021). "Both host inflammatory and vascular gelatinase B/MMP-9 has been shown to be crucial for the development of the tumour angiogenic vasculature in models of pancreatic, ovarian and skin cancer." (PMID 24473089, 2014). "We detected an increased expression rate of MMP-1 and MMP-9 in skin cancer and both genes showed the highest expression rate in AK/SCC indicated by the change-folds of MMP-1 (<10), and MMP-9 (4.70) by microarray analysis." (PMID 16893473, 2006). "In addition, O3 induces the activation of collagen degrading metalloproteinases (MMPs) MMP2 and MMP9 that play a role in photoaging and skin cancer progression." (PMID 36009203, 2022). "It is striking that the features that distinguish skin tumors developed by C-IKKα/TgAC mice, i.e., MMP-9 and VEGF-A upregulation and increased EGFR activation are the same that characterize the skin tumors arisen in mice lacking IKKα or expressing diminished levels of this protein." (PMID 27121058, 2016). "In all the patients who developed skin cancer at follow-up, NGAL, MMP-2, and MMP-9 serum levels were dosed again." (PMID 36293148, 2022). "The extract from the UE demonstrated the ability of inhibiting both cancer cell proliferation and metastasis by downregulating the skin tumor-promoting genes such as Bcl-2, STAT3, and MMP-9." (PMID 29065632, 2017). "Tumor promoting and inhibiting functions have been found for MMP9 in the human papilloma virus (HPV) 16 skin cancer model where the absence of Mmp9 reduced the number of tumors, but the tumors that formed were more aggressive." (PMID 18698413, 2008).
cardiomyopathy (18 papers, 2010 to 2025). A disease of the heart muscle or myocardium proper. "MMP9 protein was studied at 0.2–5.2 years and levels were higher in anthracycline-induced cardiomyopathy compared to control animals in studies with longer follow-up after anthracycline administration (0.32 higher ROM per year, p = 0.04)." (PMID 34052857, 2021). "Both upregulation of Timp1 and downregulation of Mmp9 in cardiac fibroblasts have been proved to preserve cardiac functions and inhibit fibrosis in cardiomyopathy." (PMID 33061247, 2020). "Similar to the intrinsic apoptotic pathway, MMP-9 was also found to be sensitive to inflammation and to participate in the pathogenesis of cardiomyopathy." (PMID 25888309, 2015). "There is a plethora of literature demonstrating that the abundance of many MMPs including MMP-9 is increased in response to a variety of cardiac insults resulting in cardiomyopathy." (PMID 25364719, 2014). "The mitigation of cardiomyopathy by tempol is reinforced by attenuation of MMP-9, TIMP-3 and induction of TIMP-4." (PMID 20828387, 2010). "On the other hand, mice with genetic ablation of TSP2 had difficulty to cope with increased cardiac loading, with augmented matrix metalloproteinase (MMP)-2 and MMP-9 activities which disrupted myocardial matrix integrity, resulting in cardiomyopathy and fatal cardiac rupture." (PMID 36335340, 2022). "This shows that this pathway is persistently activated in anthracycline-induced cardiomyopathy and that dysregulation might become more pronounced longer after anthracycline administration, possibly due to MMP9 secretion by invading immune cells." (PMID 34052857, 2021). "Ablation of a specific MMP can lead to compensatory effects, thus we next examined expression of Mmp3, which belongs to the stromelysin family, as well as examining MMP-10, Mmp2 and Mmp9, the two major MMP gelatinases that have been associated with DMD cardiomyopathy." (PMID 34947929, 2021). "We examined the role of MMP-9 in the development of cardiomyopathy in mdx mice." (PMID 25364719, 2014). "In a pressure overload model of cardiomyopathy, TSP1 knockout mice displayed reduced TGFβ1-SMAD signaling with reduced myofibroblast differentiation and increased MMP9 and MMP3 activity, an efficient activator of MMP9." (PMID 31547598, 2019). "It is known that MMP-9 activity and expression levels are elevated in cardiomyopathies but still the mechanistic outlook is not very clear." (PMID 24116115, 2013). "Considering that, in patients with ICMP, the content of MMP-9 and EDCs in the sinus blood was higher than that in the peripheral blood and, in CHD patients without cardiomyopathy, it was found to be equal, the MMP-9 hypersecretion in the myocardium probably indicates its angiodestructive effect." (PMID 37509589, 2023).
Crohn disease (18 papers, 2012 to 2024). A gastrointestinal disorder characterized by chronic inflammation involving all layers of the intestinal wall, noncaseating granulomas affecting the intestinal wall and regional lymph nodes, and transmural fibrosis. "Serum MMP-9 levels were also higher in patients with active Crohn’s disease compared with patients with inactive disease." (PMID 38203373, 2023). "According to the authors, increased MMP-9 concentrations are a reliable marker of inflammation, especially in Crohn’s disease." (PMID 38203373, 2023). "A study assessing the expression pattern of MMPs in fistulas of patients with Crohn’s disease also demonstrated elevated expression of MMP-9 (using immunohistochemical method) with MMP-2 remaining at similar level in both healthy and fistulizing tissues." (PMID 36430390, 2022). "In supernatants of homogenates from Crohn’s disease fistulas, Efsen and coworkers demonstrated that ramiprilate, the active metabolite of ramipril, inhibited MMP9 activity, dose-dependently." (PMID 35620197, 2022). "In our previous study, we have already demonstrated that in pediatric patients serum concentrations of MMP-9 correlate with indices of inflammation and reflect severity of Crohn's disease." (PMID 24803722, 2014). "They assessed the concentration of MMP-3 and MMP-9 in Crohn’s disease." (PMID 38203373, 2023). "MMP-1, MMP-3, MMP-7, MMP-8 and MMP-9 are biomarkers of Crohn’s disease." (PMID 37895400, 2023). "The results confirmed previous hypotheses that MMP-9 levels were higher in patients with Crohn’s disease compared to the control group." (PMID 38203373, 2023). "Higher MMP-9 concentrations were detected in patients with Crohn’s disease." (PMID 38203373, 2023). "The authors agree that the assessment of MMP-9 concentration in serum may help in the differentiation of Crohn’s disease." (PMID 38203373, 2023). "The MMP-9 assay is also useful in the dormant phases of Crohn’s disease." (PMID 37895400, 2023). "The aim of their study was to evaluate whether serum MMP-9 levels predict clinical exacerbation in patients with Crohn’s disease." (PMID 38203373, 2023). "In summary, the authors demonstrate that MMP-9 may be a promising marker for predicting exacerbations of the clinical phase of Crohn’s disease." (PMID 38203373, 2023). "However, given the evidence from the MR analysis, further consideration should be given to the type, dose, frequency and duration of ant-MMP9 therapy in Crohn’s disease before this target is discounted for these diseases." (PMID 32591531, 2020). "The most frequently analyzed metalloproteinases in Crohn’s disease are: MMP-1, MMP-3, MMP-7, MMP-8 and MMP-9." (PMID 37895443, 2023). "Also in the case of pediatric patients diagnosed with Crohn’s disease, the concentration of MMP-3 and MMP-9 increases with the activity of the disease." (PMID 37895400, 2023). "The aim of the study was to analyze the correlation between cyclophilin A and MMP-9 in inflammatory and non-inflammatory conditions of the large intestinal mucosa in patients with Crohn’s disease." (PMID 38203373, 2023). "In turn, the activity of MMP-9 metalloproteinases is higher in patients with Crohn’s disease, but it is not the main factor of the disease." (PMID 37895400, 2023). "For example, a comparative analysis of MMPs expression in Crohn’s disease (luminal form) and complex diverticulum disease revealed that inflamed mucosa in CD patients displayed higher expression of MMP-2, MMP-9, and MMP-13 than in diverticulitis inflamed mucosa." (PMID 36430390, 2022).
cystic fibrosis (18 papers, 2008 to 2025). Autosomal recessive disorder caused by pathogenic variants in the CFTR gene (cystic fibrosis transmembrane conductance regulator), which encodes a chloride and bicarbonate channel expressed in epithelial cells, and follow the diagnosis criteria. "MMP9, a zinc-binding endopeptidase, degrade various extracellular matrix molecules and is associated with the development of respiratory diseases, including cystic fibrosis and acute lung injury (ALI)." (PMID 40371107, 2025). "Likewise, both NE and MMP-9, which may be necessary for clearance of bacteria, are linked to airway damage and the progression of cystic fibrosis." (PMID 32295918, 2020). "It has been reported that ELA activates pro-MMP-9 in cystic fibrosis in the lung." (PMID 32429399, 2020). "Therefore, the levels of azithromycin to inhibit MMP-9 expression can be reached in the airways of cystic fibrosis patients treated with azithromycin." (PMID 28369077, 2017). "Finally, MMP-8 and MMP-9 also drive PMN recruitment to the lungs during cystic fibrosis, and this is perpetuated and amplified by MMP-9 released by PMN degranulation." (PMID 24409419, 2013). "In a recent study, in children with cystic fibrosis exposed to SHS, it was found that the MMP-9 gene is overexpressed." (PMID 32380770, 2020). "In lower airway secretions from cystic fibrosis patients, SLPI levels decrease to 30 nM while NE and MMP-9 concentrations increase up to, respectively, 10–48 nM and 7–15 nM, as determined by immunoassays." (PMID 29892293, 2018). "Notably, using a quantitative proteomic and bioinformatic approach, we identified several metalloprotease proteins usually involved in cystic fibrosis, such as matrix metalloproteinase 8 (MMP8), MMP9, and matrix metalloproteinase 16 (MMP16)." (PMID 37686190, 2023). "In human bronchial epithelial cells, expression of MMP-9 was increased when ARSB was lower, as in uncorrected cystic fibrosis cells, or following ARSB silencing." (PMID 36361933, 2022).
gastric tumor (18 papers, 2010 to 2024). "In the context of the LKB1 and PTEN loss G.C. model, the expression of MMP9 was notably increased, especially in the gastric tumor and invasive regions of the H+/K+ ATPase-Cre, LKB1L/L; PTENL/L mice." (PMID 38136437, 2023). "Later, the MMP-9 expression in gastric tumor has been confirmed to associate with poorly differentiated carcinoma, tumor stage and lymph-node metastasis." (PMID 35163805, 2022). "In particular, TSP-1 upregulates MMP-9 expression by gastric tumors, resulting in acquisition of an aggressive phenotype." (PMID 29212212, 2017). "The expression levels of CXCR4 and NFE2L2 as well as four differentially expressed NRGs (SPP1, CXCL1, MMP9, and TIMP1) were validated in gastric tumor cells and clinical samples." (PMID 38221932, 2024). "Researches have indicated that matrix metalloproteinase-9 (MMP9), a type-IV collagenase/gelatinase, is overexpressed across various tumors, including colon, breast and gastric tumors." (PMID 37242692, 2023). "Previous studies have shown that UMB inhibits gastric tumor growth and migration through inhibition of MMP2 and MMP9." (PMID 34335844, 2021). "Meanwhile, mRNA levels of NF-kB downstream metastasis-related genes including Vimentin, MMP-2, MMP-9, VEGF, ICAM-1 and VCAM-1 were significantly enhanced in the primary gastric tumors." (PMID 30728051, 2019). "We also note that the expression of several angiogenesis-related genes (Cxcl1, Cxcl2, Mmp2, Mmp9, and Vegf) was comparable among gastric tumor and non-tumor tissues from 3mo and 6mo gp130F/F and gp130F/F:Nlrp3-/- mice." (PMID 35299732, 2022).